CREB3L1 (cAMP responsive element binding protein 3 like 1)
Diseases named in the same sentence as CREB3L1 in open-access papers (continued):
Sharing a sentence is not in itself a finding about the gene and the disease.
tumor (continued). "Bioinformatics analysis revealed distinct regulatory networks between PTC and ATC, and the high expression of CREB3L1 is positively correlated with tumor stage and negatively correlated with overall survival (OS) 101-103." (PMID 38164349, 2024). "The results from this rat model of estrogen-dependent breast cancer suggests that CREB3L1 can block tumor progression and play an important role in metastasis suppression." (PMID 35802566, 2022). "The potential role of CREB3L1 in the tumor immune microenvironment was illustrated by utilizing CIBERSORT and ESTIMATE algorithms, and TISIDB online database." (PMID 36171879, 2022). "Overall, the biological functions of CREB3L1 in modulating the tumor immune microenvironment remains a research gap, which are worth exploring in future studies." (PMID 36171879, 2022). "The transcription factor CREB3L1 is identified to regulate the S100P expression and promote tumor cell invasion." (PMID 35347134, 2022). "The mice bearing the CREB3L1-knockdown cell-derived xenografts, showed a substantially lower tumor volume, compared to that in the control mice." (PMID 36192735, 2022). "Further analysis of epithelial cells showed that notable presence of CREB3L1 in ATC tumor cells, which had extremely high ECM and collagen signaling activities." (PMID 36192735, 2022). "To uncover the potential role of CREB3L1 in modulating the tumor immune microenvironment, we firstly confirmed that CREB3L1 expression levels were positively related to immune scores and stroma scores in multiple human cancers by utilizing ESTIMATE." (PMID 36171879, 2022). "The results indicated that CREB3L1 expression levels were strongly related to tumor immune cell infiltration levels in several cancer types." (PMID 36171879, 2022). "The altered expression of CREB3L1 has been reported in several tumor types, and its roles in tumorigenesis regulation has gradually been discovered." (PMID 36192735, 2022). "Next, we compared CREB3L1 expression between normal and tumor samples in TCGA pan-cancer database, and we detected significant differences in 14 cancer types among 33 types of cancer excluding those without normal tissue data (Wilcoxon test p < 0.05)." (PMID 36171879, 2022). "Further, to evaluate the effect of CREB3L1 expression on tumor growth in vivo, ATC cells with CREB3L1 knockdown were subcutaneously injected into nude mice." (PMID 36192735, 2022). "Our study showed that the expression levels of CREB3L1 in tumor cells cannot predict the response of EOC patients to DOX-based treatment based on a lack of correlation with OS, PFS, or TIL numbers." (PMID 34632049, 2021). "Immunofluorescence and FACS evaluation revealed GRP78 and CREB3L1 protein expression in the same tumor cells in the doxorubicin/paclitaxel treated TNBC cell only lines." (PMID 33042795, 2020). "We have previously reported that doxorubicin inhibits proliferation of tumor cells through proteolytic activation of CREB3L1, and CREB3L1 expression determines the sensitivity of tumors to doxorubicin in various in vitro and in vivo experimental systems." (PMID 30103710, 2018). "We then obtained unstained slides of core biopsies taken from TNBC patients before they were subjected to doxorubicin-based chemotherapy, and used 10H1 to measure CREB3L1 expression in the tumor cells through IHC." (PMID 30103710, 2018). "Deregulation of gene expression through gene fusion and/or promoter swapping is a well known mechanism behind tumorigenesis and tumor progression, but this is the first time that evidence of CREB3L1 downregulation is found in vulvar SCC." (PMID 28186972, 2017). "Overall, CREB3L1 methylation was weakly, positively correlated with tumor type (r = 0.150, p <0.05) and tumor grade (r = 0.146, p <0.05)." (PMID 26810754, 2016). "Our results suggest that CREB3L1 expression is initially upregulated in response to the stressful conditions that exist within the tumor environment, as observed for other stress response proteins." (PMID 26810754, 2016).
tumor (continued). "Overall, CREB3L1 mRNA expression was negatively correlated with tumor type (r = −0.325, p <0.00001) and tumor grade (r = −0.342, p <0.00001)." (PMID 26810754, 2016). "We observed one tumor that showed CREB3L1 DNA methylation and had relatively high CREB3L1 mRNA levels, prompting us to examine CREB3L1 gene copy number." (PMID 26810754, 2016). "We found that in luminal and HER2 amplified breast cell lines and tumors, CREB3L1 mRNA expression was frequently increased, whereas in TNBC cell lines and tumor samples, CREB3L1 expression was frequently low." (PMID 26810754, 2016). "We measured CREB3L1 mRNA expression levels by qPCR in 213 tumor samples and found that low- and medium-grade tumors had increased CREB3L1 mRNA expression when compared to normal breast tissue samples." (PMID 26810754, 2016). "Using the TCGA database, we determined if CREB3L1 mRNA expression was differentially regulated between normal tissues and the corresponding tumor tissues." (PMID 26810754, 2016). "These tumor samples generally showed less CREB3L1 DNA methylation than the cell lines had, and similar to the cell line data most methylation was clustered within the 3′ end of the region analyzed." (PMID 26810754, 2016). "The nuclear CREB3L1 was reported to inhibit tumor growth by activating transcription of genes that inhibit angiogenesis." (PMID 26110425, 2015). "Since some tumor cells were previously found to express high levels of CREB3L1 mRNA but very low levels of the protein, we determined the amount of CREB3L1 protein in these xenograft tumors by immunohistochemistry (IHC)." (PMID 26110425, 2015). "The current study demonstrates that production of CREB3L1 in tumor cells is crucial to determine their sensitivity to doxorubicin." (PMID 26110425, 2015). "The 10H1 monoclonal antibody against CREB3L1 developed in the current study makes it possible to measure CREB3L1 expression in tumor biopsies." (PMID 26110425, 2015). "We have demonstrated in the current study that this antibody can be used to measure CREB3L1 expression in tumor cells from biopsies of RCC and DLBLC." (PMID 26110425, 2015). "This analysis revealed that the amount of CREB3L1 protein was very low in XP416 even though the tumor expressed high levels of CREB3L1 mRNA." (PMID 26110425, 2015). "A new mechanism involving cleavage of a transcription factor called CREB3L1 has been proposed to explain the anti-tumour effects of doxorubicin." (PMID 23256047, 2012). "There are several tumor suppressors other than CREB3L1 that could be silenced by ROR1, suggesting that targeting ROR1 and its downstream DNMT-mediated epigenetic modifications could provide a novel therapeutic strategy for TNBC." (PMID 40427627, 2025). "Whether CREB3L1+ CB cells induced a pro-metastatic tumor microenvironment formation by secreting signals of inflammation and extracellular matrix remodeling to fibroblasts remains to be further researched." (PMID 40831537, 2025). "In addition, DOX can activate specific cellular pathways; for example, it triggers the release of the membrane-bound transcription factor CREB3L1, and tumor cells with high CREB3L1 expression are especially sensitive to DOX treatment." (PMID 40940745, 2025). "Additionally, as a transcriptional regulator, CREB3L1 is found in bone, intestinal tissue, salivary glands, prostate, and various tumor cells, where it plays significant physiological and pathological regulatory roles (51, –, 56)." (PMID 40071922, 2025). "Notably, only KPNA2 had been found in our previous study to be the crucial transporter of transcription factor CREB3L1 into the nucleus and remodel the tumor microenvironment to promote tumor growth and metastasis in ATC." (PMID 37501099, 2023). "However, a systematic assessment of CREB3L1 in pan-cancer is of absence, and the predictive value of CREB3L1 in cancer prognosis, the tumor immune microenvironment and the efficacy of immunotherapy remains unexplored." (PMID 36171879, 2022).
tumor (continued). "Therefore, exploring the relationship between CREB3L1 expression and the tumor immune microenvironment in pan-cancer is vital." (PMID 36171879, 2022). "In other studies, ARNT2, CREB3L1, GLI3, and PBX3 have been associated with tumor progression." (PMID 33924679, 2021). "The purpose of this study is to determine whether CREB3L1 expression in tumor cells of TNBC patients can be established as a biomarker to predict outcomes of doxorubicin-based chemotherapy." (PMID 30103710, 2018). "In patients with this tumor subtype, CREB3L1 expression is predictive of distant metastasis." (PMID 29057869, 2017). "Immunohistochemistry for expression of CREB3L1 showed a score value from 0 to 3 for each tumor." (PMID 28186972, 2017). "In addition, we characterize CREB3L1 mRNA expression, gene methylation and protein localization in a large number of human tumor samples." (PMID 26810754, 2016). "We observed that CREB3L1 DNA methylation was found in some samples within all tumor grades." (PMID 26810754, 2016). "To assess whether there was any relationship between different tumor subtypes and either overall CREB3L1 protein expression and/or subcellular localization, we needed to determine their HER2 status." (PMID 26810754, 2016). "In all we analyzed 201 tumor samples and found 35 contained CREB3L1 methylation." (PMID 26810754, 2016). "Tumors form in a stressful cellular environment with low nutrients and low oxygen levels (hypoxia), suggesting that CREB3L1 may be activated during tumor development and progression." (PMID 26810754, 2016). "The subcellular localization of CREB3L1 also changes with tumor progression." (PMID 26810754, 2016). "Interestingly, CREB3L1 is down regulated in bladder cancer and acts as a tumor suppressor by directly suppressing tumor cell migration and colony formation." (PMID 27121396, 2016). "In addition to genes that inhibit tumor growth, the nuclear from of CREB3L1 also activates genes required for assembly of collagen-containing extracellular matrix." (PMID 26110425, 2015). "When we analyzed DLBLC, we also tried to determine whether higher expression of CREB3L1 in tumor biopsies before chemotherapy was correlated to better responses to later treatment with doxorubicin." (PMID 26110425, 2015). "Importantly, the down-regulation of CREB3L1 diminishes doxorubicin-induced effects on cell proliferation, whereas overexpression of CREB3L1 makes tumour cells more sensitive to doxorubicin." (PMID 23256047, 2012). "However, several other studies have demonstrated CREB3L1 as a tumor suppressor in TNBC patients." (PMID 40427627, 2025). "In addition, the roles of CREB3L1 in a specific cancer type remain unclear, and the mechanisms by which CREB3L1 modulates the tumor immune microenvironment are still unknown." (PMID 36171879, 2022). "Furthermore, the results of GSEA analysis showed that CREB3L1 was obviously involved in modulating the immune response, immune relevant pathways and chemokine release in pan-cancer, further confirming the potential roles of CREB3L1 in the tumor immune microenvironment." (PMID 36171879, 2022). "Our study sheds highlight on the promising role of CREB3L1 as a prognostic biomarker, and an effective predictor for the immunotherapeutic efficacy and drug sensitivity in pan-cancer, as well as the potential mechanism by which CREB3L1 modulates the tumor immune microenvironment." (PMID 36171879, 2022). "These included cancer epigenetic targets previously implicated in tumor suppressive activity such as ANXA6 [annexin A6], VANGL2 [VANGL planar cell polarity protein 2], BIN1 [bridging integrator 1], and CREB3L1 [cAMP responsive element binding protein 3 like 1]." (PMID 34074348, 2021). "The recent development of Nr4a1 agonists that directly bind and activate Nr4a1 may be useful pharmacological tools to increase Creb3l1 expression in tumor cells, but our data shows that this would certainly depend on the methylation status of the Creb3l1 promoter." (PMID 29311806, 2017).
tumor (continued). "Thus, CREB3L1 may provide a cytoprotective effect early in tumor development and later decreased expression allows progression to high-grade tumors." (PMID 26810754, 2016). "Thus, measuring CREB3L1 expression in tumor cells may be useful in identifying cancer patients who are most likely to benefit from doxorubicin treatment." (PMID 23256041, 2012). "Our results establish a pathway suggesting ROR1 as a potential therapeutic target for reversing the epigenetic silencing of tumor suppressor genes in TNBC and other malignancies that have low CREB3L1 expression." (PMID 40427627, 2025). "In GH3 xenograft nude mice, administration of deguelin (4 mg/kg, i.p., every other day for two weeks) significantly inhibited tumor growth with significant reduction in both AKT phosphorylation and CREB3L1 levels in deguelin-treated xenografts." (PMID 41184622, 2025). "We also found fewer collagen fibers and myofibroblasts in ATC cell-derived xenografts after CREB3L1 knockdown, implying that CREB3L1 drives the aggressiveness of ATC, mainly through regulating the tumor stromal microenvironment." (PMID 36192735, 2022). "The differential expression in GRNs identified in each patient also confirmed the tumor heterogeneity of SBA, with transcription factors (TFs) such as BATF, CREB3L1, KLF2, E2F1 variably expressed among different patients." (PMID 36104333, 2022). "Our findings recognize the crucial role of CREB3L1 in driving invasion, metastasis, and growth of ATC tumors by shaping the tumor stromal microenvironment." (PMID 36192735, 2022). "Based on the integrative analysis of multi-omics and multiple tumor models, we revealed that CREB3L1 facilitated the growth and metastasis of ATC tumors by activating the ECM signal and remodeling the tumor stromal microenvironment." (PMID 36192735, 2022). "The CREB3L1 expression level was compared with progression-free survival (PFS) and the score of tumor-infiltrating lymphocytes (TILs), previously reported to be associated with improved PFS." (PMID 34632049, 2021). "The current study elucidates a potential new strategy for the treatment of metastatic TNBC based on the modulation of CREB3L1 and cell-surface GRP78 expression by chemotherapy in addition to GRP78-targeted drugs for the elimination of tumor-initiating clones." (PMID 33042795, 2020). "Doxorubicin blocks the proliferation of cancer cells through proteolytic activation of CREB3L1, whereas T-VEC kills tumor cells via lytic replication." (PMID 33076370, 2020). "To validate the essential role of CREB3L1, E2F7, FOXM1, and NFYB in ATC progression, we detected their gene expression levels in both human tumor tissues and cell lines." (PMID 31183379, 2019). "In conclusion, our finding reveals that GTSE1+ OB cells and CREB3L1+ CB cells enrich in metastatic OS, and a coordinated pro-metastatic tumor microenvironment driven by cancer cells and non-malignant cells." (PMID 40831537, 2025). "Interestingly, our findings showed that CREB3L1 expression was abnormally decreased in BLCA, and CREB3L1 expression was increased during tumor stage progression in patients with BLCA, which seems to be contradictory." (PMID 36171879, 2022). "Therefore, after demonstrating the impact of chemotherapy on the expression of GRP78 and CREB3L1 in TNBC, we examined the correlations between the protein expression patterns and the tumor migration capacities using two different techniques." (PMID 33042795, 2020).
tumor (continued). "Recent reports suggest that doxorubicin inhibits tumor cell proliferation through proteolytic activation of CREB3L1 and not by induction of DNA damage." (PMID 33042795, 2020). "We hypothesized that chemotherapy drugs trigger endoplasmic reticulum stress and promote cell-surface expression of GRP78 and CREB3L1 activation through the UPR pathway, thereby preventing progression of tumor metastasis." (PMID 33042795, 2020). "As a result, doxorubicin inhibited proliferation of tumor cells cultured in vitro that express CREB3L1 but not those in which expression of the gene was inhibited, even though DNA damage induced by the drug was indistinguishable among these cells." (PMID 30103710, 2018). "These in vitro and in vivo results suggest that doxorubicin inhibits tumor cell proliferation through proteolytic activation of CREB3L1 but not DNA damage." (PMID 30103710, 2018). "While CREB3L1 inhibition does not affect primary tumor formation or growth, as indicated by similar tumor weights and Ki67-positive proliferative indices, there was a >80-fold reduction in the number of circulating tumor cells (CTCs)." (PMID 29057869, 2017). "Although the sample size within each group was small, there was a larger proportion of HER2 amplified tumor samples with cytoplasmic CREB3L1 protein, rather than nuclear CREB3L1." (PMID 26810754, 2016). "The tumor with CREB3L1 DNA methylation but high CREB3L1 mRNA levels had a normal gene copy number (data not shown)." (PMID 26810754, 2016). "Using tumor cells cultured in vitro, we reported that doxorubicin inhibited proliferation of cells expressing CREB3L1 but not those in which the gene was not expressed, even though the drug was equally effective in triggering DNA damage in both cells." (PMID 26110425, 2015). "As both SFRP1 and CREB3L1 could inhibit tumor proliferation, reduced CREB3L1 expression could not inhibit CCA proliferation, we excluded CREB3L1 and STK11 from our analysis." (PMID 27385214, 2016). "Thus, at least for tumors expressing high levels of CREB3L1, doxorubicin appears to inhibit tumor growth by triggering proteolytic activation of CREB3L1 rather than stimulating DNA damage." (PMID 26110425, 2015). "Moreover, the role of CREB3L1 in modulating the tumor immune microenvironment is still largely unknown, and no systematic pan-cancer investigation has focused on CREB3L1." (PMID 36171879, 2022). "Interestingly, we noticed that altered CREB3L1 expression did not affect cancer cell proliferation or ATC cell-derived sphere size, but suppressed tumor growth in vivo." (PMID 36192735, 2022).